NR4A2 (nuclear receptor subfamily 4 group A member 2)
Diseases named in the same sentence as NR4A2 in open-access papers (continued):
Sharing a sentence is not in itself a finding about the gene and the disease.
schizophrenia (continued). "Our results are consistent with previous studies that show that the NR4A2 gene dosage is significantly related to cognitive function in animal models of schizophrenia." (PMID 33563249, 2021). "This study aimed to analyze two variants and the expression levels of the NR4A2 gene with susceptibility to schizophrenia, as well as to evaluate whether possession of NR4A2 variants influence the possible correlation between gene expression and working memory performance in schizophrenia." (PMID 33563249, 2021). "This is the first study to identify a positive correlation between NR4A2 gene expression levels and working memory function in schizophrenia patients." (PMID 33563249, 2021). "The NR4A2 gene (also known as Nurr1) has been related to schizophrenia etiology and cognitive function." (PMID 33563249, 2021). "This graph shows that only in 3C/3C rs34884856 patients, a decrease of NR4A2 mRNA expression was related to BDS impairment in schizophrenia." (PMID 33563249, 2021). "A putative relationship between Nr4a2 and schizophrenia was further supported by studies with rodents." (PMID 34880728, 2021). "It is important to mention that this is the first study to analyze the association of two genetic variants of the NR4A2 gene (rs34884856 in promoter and rs35479735 in intron 6) and NR4A2 mRNA expression with working memory deficits in schizophrenia." (PMID 33563249, 2021). "A recent study with NR4A2 knock-out mice suggests that these animals display behavioral endophenotypes that are displayed in other animal models of psychosis/schizophrenia." (PMID 18992145, 2008). "Thus, it would be also important to address the impact of Nr4a2 on behavioral and psychological symptoms with new studies in animals’ models for these diseases such as schizophrenia or autism spectrum disorder." (PMID 34880728, 2021). "Nr4a2 heterozygous mice displayed a pleiad of symptoms and behaviors related to schizophrenia." (PMID 34880728, 2021). "Furthermore, decreased expression of the NR4A2 gene was found in the dorsolateral prefrontal cortex (DLPFC) of patients with schizophrenia." (PMID 33563249, 2021). "We detected decreased expression of RARG and NR4A2 mRNAs in females with schizophrenia (p<0.05)." (PMID 27992436, 2016). "The region contains potential susceptibility genes for schizophrenia, like HNMT (Histamine N-methyltransferase) and NR4A2 (alias NURR1, nuclear receptor subfamily 4, group A, member 2, an orphan nuclear receptor and putative transcription factor for the dopamine transporter)." (PMID 21897869, 2011). "It is important to emphasize that the differences between the populations analyzed in other studies, as well as environmental and epigenetics factors, cannot be ruled out, as well as the possibility that NR4A2 is not relevant in the susceptibility to schizophrenia." (PMID 33563249, 2021). "This study presents evidence for down-regulation of the nuclear receptors NR4A1, NR4A2, RXRB, and KLF4 mRNAs in the DLPFC in schizophrenia and evidence of reduced RARG and RXRG expression in females with schizophrenia." (PMID 27992436, 2016). "This study reports significant changes in the nuclear receptors NR4A1, NR4A2, and RXRB and KLF4 in schizophrenia and provides further evidence of a role for the nuclear receptors in the disease process." (PMID 27992436, 2016). "Therefore, a decrease in dopaminergic neurotransmission in those brain regions could be related to the cognitive deficits in this psychiatric disorder, in particular, the decrease in the NR4A2 gene in the left DLPFC (area involved in working memory, mainly auditory) in schizophrenia patients." (PMID 33563249, 2021).
Alzheimer disease (28 papers, 2015 to 2025). A progressive, neurodegenerative disease characterized by loss of function and death of nerve cells in several areas of the brain leading to loss of cognitive function such as memory and language. "The expression of Foxa2 and nuclear receptor subfamily 4 group A member 2 (Nurr1) mediated by adeno-associated virus can alleviate cognitive deficits in mice with Alzheimer’s disease." (PMID 39859532, 2025). "This correlation between NR4A2 deficiency and cognitive skills has been found in other animal models for Alzheimer’s disease and attention-deficit hyperactivity disorder as well as its particular role in memory tasks as reported in preclinical studies." (PMID 33563249, 2021). "Incidentally, specific transcription factors, such as Nr4a2 and FosB, have been implicated in the processing of odor information, with alterations in their expression correlating with early olfactory dysfunction in Alzheimer’s disease mouse models." (PMID 38892173, 2024). "The association of NR4A2 deficiency and reduction in performance on cognitive tasks has been reported for Alzheimer’s disease and attention-deficit hyperactivity disorder animal models, as well as with reports of its important role in diverse memory tasks in preclinical studies." (PMID 33563249, 2021). "While the role of NR4A2 in PD has been best described, more recent reports have demonstrated its role in Alzheimer’s disease, multiple sclerosis, stroke, depression, and intellectual disability." (PMID 37887305, 2023). "One of the first brain diseases, besides PD, that was related to Nr4a2 was Alzheimer’s disease (AD)." (PMID 34880728, 2021). "Notably, the CRTC1-dependent regulation of NR4A2 gene expression is suppressed by the presence of amyloid beta in an animal model of Alzheimer’s disease." (PMID 41009723, 2025). "Also, its role in neurodegenerative diseases, such as Parkinson’s or Alzheimer’s disease, is examined, as well as a brief exploration on recent proposals to develop novel therapies for these neurological diseases based on small molecules that could modulate NR4A2 transcriptional activity." (PMID 38791237, 2024).
breast carcinoma (15 papers, 2013 to 2025). "A functional role for NR4A2 has been suggested by a study examining the mechanisms behind obesity-associated breast cancer risk." (PMID 33634114, 2021). "They showed a higher NR4A2 expression level in the normal breast epithelium compared to breast carcinoma cells, which strongly correlated with an increase in relapse-free survival in a cohort of breast cancer patients." (PMID 35547878, 2022). "Individually, FOS and NR4A2 have been identified as potential drug targets and biomarkers for breast cancer." (PMID 34161324, 2021). "This is in agreement with the growth-inhibitory effect of NR4A2 silencing detected in breast cancer, colon cancer and intestinal epithelial cells and suggests a different role for NR4A2 in HSCs and HPCs proliferation." (PMID 28098757, 2017). "In primary breast-cancer, NR4A2 expression is inversely correlated with lymph-node metastases and directly correlated with increased relapse-free survival, suggesting onco-suppressive properties." (PMID 26894976, 2016). "However, NR4A2-silenced breast xenografts models showed significantly decreased growth compared to the control model, showing a biphasic role for NR4A2 in breast cancer progression." (PMID 35547878, 2022). "NR4A2 mRNA overexpressed in both luminal A and luminal B breast cancer relative to other subtypes." (PMID 35547878, 2022). "In addition, NR4A1 and NR4A2 mRNA expressions are lower in basal breast cancer when compared to other subtypes of breast cancer." (PMID 35547878, 2022). "In breast cancer, it has been suggested that NR4A2 has a dichotomous role." (PMID 34161324, 2021). "When NR4A2 expression and activity are depleted in isolated human ASCs, there is a substantial increase in aromatase gene expression and, therefore, estrogen biosynthesis, increasing the likelihood of breast cancer occurrence." (PMID 33634114, 2021). "NR4A2 inhibits aromatase expression in mammary-gland stromal adipocytes and this action may have implications for breast-cancer prevention, as obesity and estrogen production are breast-cancer risk-factors." (PMID 26894976, 2016). "The few data available in mammary-tumors support therapeutic strategies based on NR4A2-agonists." (PMID 26894976, 2016). "NR4A1 has been found to bind to the NBRE or coactivator SWI/SNF complex response elements by NR4A2 or PPARγ, resulting in the change of fatty acid-related genes ACOX, CPT1M, FABP2, and FABP4 in melanoma and breast cancer." (PMID 36052242, 2022). "Modulating the expression levels of NR4A1, NR4A2, and NR4A3 can be a potential therapeutic approach for breast cancer." (PMID 35547878, 2022). "With a genome-wide cDNA screen, it was identified that inflammation-induced NR4A1 (NR4A2 and NR4A3 also respond) is a critical factor for the activation of TGF-β/SMAD-mediated breast cancer cell migration, invasion, and metastasis in vitro and in vivo." (PMID 33634114, 2021). "Both compounds inhibited breast cancer cell growth and induced apoptosis and there was a concordance between the effects of NR4A1 and NR4A2 knockdown and effects of DIM-3,5 analogs in MDA-MB-231 cells and on several NR4A-regulated genes including EGFR, β1-integrin, bcl-2 and c-Myc." (PMID 40313760, 2025). "Both compounds inhibited breast cancer cell growth and induced apoptosis and there was a concordance between the effects of NR4A1 and NR4A2 knockdown and effects of DIM-3,5 analogs in TNBC cells and on several NR4A-regulated genes including EGFR, β1-integrin, bcl-2 and c-Myc." (PMID 41184246, 2025). "The significance of NR4A family member NURR1 (NR4A2) in breast cancer etiology has not been elucidated." (PMID 23517088, 2013).
multiple sclerosis (15 papers, 2010 to 2026). A progressive autoimmune disorder affecting the central nervous system resulting in demyelination. "For instance, in a mouse model of multiple sclerosis, abnormal NR4A2 expression enhanced the promoter activity of interleukin-17 and interferon-gamma genes, resulting in excessive cytokine production." (PMID 39512681, 2024). "We have previously reported that NR4A2 is among the genes expressed by circulating T cells that are highly upregulated in patients with multiple sclerosis (MS) and that NR4A2 is also induced in T cells during rodent EAE." (PMID 23437182, 2013). "NR4A2 is also known to play a central role in eliciting the production of inflammatory cytokines in multiple sclerosis (MS (MIM 126200))." (PMID 20174570, 2010).
depression (14 papers, 2017 to 2025). "Nr4a2 reduction has also been implicated in depression, where it mediates the decrease in neuronal activity induced by lipopolysaccharide (LPS), leading to the development of depressive symptoms." (PMID 38366763, 2024). "In this regard, it has been reported that NR4A2 (Nurr1) heterozygous (+/−) mice exhibited a depression-like behavior, indicating difficulties in coping with stress." (PMID 41009723, 2025). "Furthermore, it has been reported that using this particular model of depression-like behavior in adult mice led to a rapid increase in NR4A2 (Nurr1) mRNA expression in specific brain regions following a second exposure to the forced swim test." (PMID 41009723, 2025). "In particular, there are several preclinical models for studying depression in which the role of NR4A2, also known as Nurr1, has been described." (PMID 41009723, 2025).
bladder cancer (13 papers, 2012 to 2024). "In that study, high levels of cytoplasmic NR4A2 were associated with adverse outcome in bladder cancer patients." (PMID 30266952, 2018). "Recently, some studies reported that nuclear receptors (NRs) such as Nur77 (NR4A1) and Nurr1 (NR4A2) were involved in bladder cancer progression." (PMID 25878394, 2015). "Contrary to the findings in bladder cancer cells, NR4A2 is shown to promote growth of colorectal cancer and to transactivate osteopontin, a direct target of the Wnt/β-catenin pathway associated with colorectal invasion and metastasis." (PMID 24086717, 2013). "NR4A2 is highly expressed in several bladder cancer cell lines and activation of the ligand-binding domain of NR4A2 was demonstrated to induce apoptotic pathways and inhibit growth of bladder cancer established in nude mice." (PMID 24086717, 2013). "For instance, NR4A2 exhibits oncogenic functions in cervical, prostate, and colon cancers by promoting malignant transformation and refraining intrinsic apoptosis, while acting as a tumor suppressor in bladder cancer by eliciting cell apoptosis." (PMID 38570607, 2024).
Obesity (13 papers, 2016 to 2025). Accumulation of substantial excess body fat. "It has been reported that NR4A2 plays important roles in cancer, obesity, diabetes and neurological disease; our results reported a new role for NR4A2 in ischemic heart diseases." (PMID 29531824, 2018). "Similarly, other reports highlighted the epigenetic influence of low-grade inflammation induced by maternal hyperinsulinemia, obesity, and disrupted gut microbiome on the expression of NR4A2 during prenatal/early-life exposome of offspring." (PMID 40564942, 2025). "Moreover, upregulation of three NRs such as NR4A1, NR4A2, and NR4A3 can be used for the potential biomarkers for obesity while downregulation of NR1D1 can be used as a potential biomarker for obesity with rheumatoid arthritis as a complication." (PMID 29065888, 2017).
Cognitive impairment (12 papers, 2019 to 2026). Abnormal cognition is characterized by deficits in thinking, reasoning, or remembering. "Altered NR4A2 expression is thought to have caused the neurological phenotype of P1, characterized by epilepsy with psychomotor delay and cognitive impairment." (PMID 35407632, 2022). "Future studies should improve our knowledge of the role of Nr4a2 in the cognitive impairment associated to several brain pathologies." (PMID 34880728, 2021). "Thus, NR4A2 gene dysregulation has been implicated in PD, AD progression, SZ, substance abuse (alcohol and cocaine), NDDs and cognitive impairment." (PMID 41009723, 2025). "Most studies on NR4A2 activators in neurodegenerative and psychiatric diseases have focused on PD, AD and cognitive impairments." (PMID 41009723, 2025). "NR4A2 is also involved in neurodevelopmental disorders and cognitive deficits as reported in clinical trials." (PMID 33563249, 2021). "Furthermore, clinical studies have identified NR4A2 as a potential contributor to a range of dopamine neuron-related pathologies, including PD, cognitive deficits, developmental disorders, SZ, and AD." (PMID 41009723, 2025). "Thus, a cross-species impairment of Nr4a2 hippocampal expression is observed in mice and rats with cognitive deficits." (PMID 34880728, 2021).
diabetes (11 papers, 2013 to 2026). "Recurrent hypoglycaemia in the absence of diabetes was associated with changes in a small subset of genes associated with endothelial integrity, β-adrenergic signalling and heart failure, including Cldn5, Akap12, Nr4a2 and Adamts4." (PMID 41212210, 2026).
lung carcinoma (11 papers, 2016 to 2025). "The KM plotter analysis for the transcription factors identified during the present study revealed a statistically significant association between the expression levels of YY1 and NR4A2 with the survival of lung cancer patients." (PMID 31867044, 2019). "NR4A2 is downregulated in lung cancer and overexpressed in PAH dataset, suggesting an association with tumoral processes during early stages of lung cancer related to this lung disease." (PMID 31867044, 2019). "Furthermore, NR4A2 is implicated in the proliferation of lung cancer cell lines." (PMID 40361912, 2025). "NR4A2 is downregulated in five lung cancer datasets and overregulated in PAH dataset." (PMID 31867044, 2019). "The four TFs (YY1, ZEB1, NR4A2 and E2F1) found coexpressed and identified with the DAVID-Opossum analysis have evidence of its association with tumorigenic processes, that could relate them to establishment of lung cancer." (PMID 31867044, 2019). "miRNA-DEG-TF network analysis revealed NR4A2 as the most frequently targeted gene, regulated by multiple miRNAs and TFs, suggesting its role as a key molecular hub linking COPD and lung cancer." (PMID 40826767, 2025). "E2F1, NR4A2, and ZEB1 reappear coexpressed in the LCII network, further verifying their importance for the establishment and progression of lung cancer since they are also in the LC&LD network and in the LCI network." (PMID 36101460, 2022). "NR4A2 and E2F1 function have been related with resisting to cell death and sustaining a proliferative signal processes in lung cancer." (PMID 31867044, 2019). "These individual CRTC knockout cells showed a reduction in expression of several CREB-mediated target genes, such as PDE4D, INSL4, LINC00473, and NR4A2, but not to the extent of their endogenous levels in LKB1-wt lung cancer H522 cells, as assayed by western blotting or RT-qPCR assays." (PMID 34142658, 2021).
glioblastoma (10 papers, 2021 to 2025). The most malignant astrocytic tumor (WHO grade IV). "Specifically, in glioblastoma, microglia subjected to oxidative stress shows an increased binding of nuclear receptor subfamily 4 group A member 2 (NR4A2) to the promoter region of the SQLE gene." (PMID 40270603, 2025). "Moreover, dual NR4A1/NR4A2 regulation of TWIST1 in glioblastoma cells has also recently been reported using a similar approach." (PMID 40332813, 2025). "NR4A2, a member of the nuclear receptor transcription factor superfamily, modulates the immune microenvironment of glioblastoma, enhancing, CD8+ T cell antigen presentation, microglial plasticity, and the therapeutic efficacy of immune checkpoint blockade in vivo." (PMID 39098992, 2024). "Moreover, the DIM-3,5 and DIM8-3,5 analogs also decreased NR4A1- and NR4A2-dependent transactivation in U87G glioblastoma cells transfected with GAL4-NR4A1 or GAL4-NR4A2 chimeras and a UAS-luciferase reporter gene construct." (PMID 38540704, 2024). "In summary, results of this study demonstrate that DIM-3,5 and DIM8-3,5 analogs bind both NR4A1 and NR4A2, activate NR4A1- and NR4A2-dependent transactivation, and, like other DIM analogs, these compounds are cytotoxic to colon and glioblastoma cells." (PMID 38540704, 2024). "Research has shown that single-cell sequencing of glioblastoma multiforme (GBM) reveals that microglia are in a state of severe oxidative stress, inducing NR4A2-dependent transcriptional activity in these cells." (PMID 39156969, 2024). "Additionally, microglia within glioblastoma (GBM) microenvironments frequently experience high oxidative stress, triggering an imbalance in lipid metabolic homeostasis via the NR4A2/SQLE pathway and subsequently impairing antigen-presenting capacity." (PMID 39506843, 2024). "The selected GSC superenhancers were enriched for transcriptional motifs, including NR4A2, SMAD3, and ETV4, which have been previously reported to promote glioblastoma malignancy." (PMID 36394953, 2023). "Recent research also suggests that NR4A2 is a negative prognostic factor in glioblastoma, with the suppression of NR4A2 leading to reduced tumor growth and invasiveness." (PMID 40361912, 2025). "The GAL4-NR4A2-dependent transactivation is cell context-dependent and is induced in colon and pancreatic cancer cells and decreased in U87MG glioblastoma cells, whereas CDIM compounds that bind NR4A2 decrease cell viability in colon, pancreatic cancer and glioblastoma cells." (PMID 40332813, 2025). "Pharmacological inhibition of the NR4A2-SQLE axis has been shown to reduce immunosuppression and improve the efficacy of ICB therapies, highlighting its potential as a therapeutic target in glioblastoma." (PMID 40270603, 2025).